LPL (lipoprotein lipase)
Diseases named in the same sentence as LPL in open-access papers (continued):
Sharing a sentence is not in itself a finding about the gene and the disease.
Cirrhosis (3 papers, 2019 to 2025). A chronic disorder of the liver in which liver tissue becomes scarred and is partially replaced by regenerative nodules and fibrotic tissue resulting in loss of liver function. "Among all, the top 5 hub genes identified for NAFLD vs. control were CXCL9, NOS2, SERPINE1, FABP4, and LPL, whereas AKR1D1, UGT2B17, CYP26B1, LIPC, and DGAT2 were identified as the top 5 hub genes for the NAFLD vs. cirrhosis group." (PMID 40365443, 2025). "Additionally, the top 5 biological functional hub genes in NAFLD vs. control (CXCL9, NOS2, SERPINE1, FABP4, and LPL) and NAFLD vs. cirrhosis (AKR1D1, UGT2B17, CYP26B1, LIPC, and DGAT2) groups were identified through PPI analysis among lipid, immune, and metabolism dysregulated genes." (PMID 40365443, 2025).
cognitive deficits (3 papers, 2015 to 2023). "Our study has shown that the TBI patients with cognitive deficits had lower serum LPL levels, which is consistent with previous reports that LPL-deficient mice display memory impairments." (PMID 28251161, 2017). "Thus, NEXLPL+/- mice can serve as a preclinical model to study cognitive deficits and other behavioral alterations that might also be present in LPL heterozygous deficient human." (PMID 26263173, 2015). "Decreased plasma level of lipoprotein lipase predicted early cognitive deficits." (PMID 37904406, 2023). "Additionally, we found that lipid metabolism-associated DEPs, including ApoC-II, Apo(a), cholesteryl ester transfer protein (CETP), and LPL, were significantly altered in the TBI patients with cognitive impairment." (PMID 28251161, 2017). "Interestingly, our results revealed that AD signaling pathways (including LPL, GAPDH, and CaM) might play an important role in the pathophysiology of post-TBI cognitive impairments." (PMID 28251161, 2017).
dementia (3 papers, 2017 to 2025). Loss of intellectual abilities interfering with an individual's social and occupational functions. "An effect of PCSK9, ANGPTL4, and LPL variants on dementia risk cannot be excluded." (PMID 41059729, 2025). "Previous studies have demonstrated that LPL is highly expressed in the pyramidal cells of the hippocampus and involved in the pathogenesis of dementia." (PMID 28251161, 2017).
depression (3 papers, 2022 to 2025). "Among all tested associations, two variables—LPL-Depression and LPL-Anxiety—showed statistically significant differences, suggesting that LPL expression may vary between groups when stratified by depressive symptoms and anxiety levels." (PMID 41464486, 2025).
diabetic cardiomyopathy (3 papers, 2021 to 2025). Diabetic cardiomyopathy is a disorder of the heart muscle in people with diabetes. "Further, modulation of VEGF-B presents a novel route of therapeutic rescue of the LPL activity to improve cardiac outcomes in diabetic cardiomyopathy." (PMID 41373652, 2025). "This positions the VEGF-B/LPL axis as a promising, albeit experimentally validated, therapeutic target for diabetic cardiomyopathy." (PMID 41373652, 2025). "Several lines of transgenic mice, especially those overexpressing long-chain acyl-CoA synthetase in cardiomyocytes, fatty acid transport protein 1, lipoprotein lipase (LpL), or PPARα using the α-myosin heavy chain promoter, exhibited similar phenotypes to diabetic cardiomyopathy." (PMID 38706718, 2024). "Elevated FA increased the expression lipoprotein lipase (LPL) and FA transport protein (FATP) leading to an increase in FA utilization and eventually diabetic cardiomyopathy." (PMID 34405550, 2021).
gastric cancer (3 papers, 2017 to 2025). A primary or metastatic malignant neoplasm involving the stomach. "Meanwhile, previous studies have demonstrated that LPL expression is decreased in NSCLC through IF or IHC techniques, while it is significantly overexpressed in gastric cancer." (PMID 40427755, 2025). "In N+ gastric cancer, leptin-induced phosphorylation of angiopoietin-like protein 4 (ANGPTL4) enhances lipid uptake via overexpressed lipoprotein lipase (LPL), thereby stimulating prostaglandin E2 (PGE2) production and ultimately facilitating lymph node metastasis." (PMID 40977700, 2025). "Although there have been many studies using IF or IHC techniques to detect the expression of LPL in various diseases such as gastric cancer and NSCLC, there are no reports on the expression differences of LPL in normal tissues and LUAD tissues using IF or IHC techniques." (PMID 40427755, 2025).
gout (3 papers, 2013 to 2021). A condition characterized by painful swelling of the joints, which is caused by deposition of urate crystals. "The therapeutic targets through which Simiao decoction alleviated gouty arthritis were p-STAT3, APOB, CASP8, c-FOS, PPARα, FN1, and LPL." (PMID 32670069, 2020).
hyperlipemia (3 papers, 2022 to 2025). "Chronic hypernatremia likely causes a gradual, sustained inhibition of LPL, contributing to hyperlipemia in vivo." (PMID 40646895, 2025). "These inflammatory mediators also affect lipoprotein lipase activity and increase the serum lipid levels (hyperlipemia)." (PMID 35625570, 2022). "Furthermore, IR may result in an increased rate of fat breakdown and reduced activity of lipoprotein lipase in adipose tissue, which in turn could lead to hyperlipemia and excessive the production of UA." (PMID 37513557, 2023).
hyperthyroidism (3 papers, 2006 to 2024). Overactivity of the thyroid gland resulting in overproduction of thyroid hormone and increased metabolic rate. "In contrast, LPL activation, known as the primary action of ANGPTL3 inhibitors, was found to be related to an increased risk of hyperthyroidism." (PMID 38425755, 2024). "Genetic mimicry of LPL activation was significantly associated with the increased level of FT4 within reference range (β = 0.098; 95% CI 0.041 to 0.156; P = 0.001), partially supporting the observed detrimental effect of genetically proxied LPL activation on hyperthyroidism risk above." (PMID 38425755, 2024).
idiopathic pulmonary fibrosis (3 papers, 2014 to 2025). Idiopathic pulmonary fibrosis (IPF) is a nonneoplastic pulmonary disease that is characterized by the formation of scar tissue within the lungs in the absence of any known cause. "CD36-null cells have increased expression of LPL, IL-6 and IL1-β which have been implicated in inflammasome assembly during bleomycin induced pulmonary fibrosis." (PMID 38098035, 2023). "miR-410 is involved in the regulation of lipoprotein lipase levels, muscle regeneration, and idiopathic pulmonary fibrosis." (PMID 25272045, 2014). "One of the most comprehensive resources for lung cell data is the Human Lung Cell Atlas, which has identified a population of SPP1+ macrophages co‐expressing LPL and CHIT1 across various disease conditions, including COVID‐19 and idiopathic pulmonary fibrosis (IPF)." (PMID 40395129, 2025).
kidney damage (3 papers, 2011 to 2025). "In summary, renal LPL plays a crucial role in the pathophysiology of lipid metabolism and the pathogenesis of nephropathy, and activation of renal LPL is renoprotective in diet-induced DN." (PMID 21762526, 2011). "We did not determine a significant difference between the HPL and LPL groups; however, further studies with more specific kidney damage markers are needed to clarify the effect of different energy sources and power settings on kidney functions." (PMID 38340151, 2024). "The expression level of the LPL gene was negatively correlated with M1 and M2 macrophages, suggesting that LPL may affect the pro-inflammatory microenvironment of DKD by regulating the polarization state of macrophages, thereby exacerbating kidney damage." (PMID 40747306, 2025).
Lipedema (3 papers, 2020 to 2024). Disorder of adipose tissue characterized by symmetric and bilateral enlargement of the lower extremities due to abnormal deposition of subcutaneous fat often in obese women. "Adipocytes differentiated from lipedema ASCs-T and ASCs-A showed an increase in adiponectin, LPL and CD36 gene expression compared to the same cells from healthy ASCs." (PMID 32059474, 2020). "Gene expression of the primary adipogenic genes PPAR-γ (p < 0.001), LPL (healthy p < 0.05; lipedema p < 0.001), and Glut 4 (healthy p < 0.01; lipedema p < 0.001), were significantly increased in differentiated spheroids in both groups compared to undifferentiated spheroids." (PMID 33171717, 2020). "Estrogen also regulates leptin and lipoprotein lipase genes (LPL) and increases angiogenesis and vascular endothelial growth factor (VEGF) expression, a phenomenon observed in the SAT of lipedema patients." (PMID 38791004, 2024). "We analyzed the expression of the primary adipogenic (ADIPOQ, LPL, PPAR-γ and Glut4) and ECM-remodeling (collagen, FN, LN, ITAGA5, MMP2, 9 and 11) markers at the transcriptional level and by immunohistochemistry in 3D spheroids derived from ASCs from both lipedema and healthy individuals." (PMID 33171717, 2020).
lipoma (3 papers, 2012 to 2025). A benign, usually painless, well-circumscribed lipomatous tumor composed of adipose tissue. "In a study on lipomas, increased lipoprotein lipase activity was implicated in the development of the abnormal adipose tissue masses." (PMID 22300160, 2012). "It is possible that changes in triglyceride metabolism modulate LPL activity within adipose tissue, thereby affecting lipoma formation." (PMID 40225498, 2025). "However, the relationship between systemic lipid alterations and local LPL activity in lipoma development remains unclear." (PMID 40225498, 2025). "This may be due to high lipoprotein lipase activity in neoplastic lipoma cells." (PMID 25815220, 2015). "As estrogen modulates lipid metabolism and LPL activity in a depot- and condition-dependent manner, HRT-related estrogen supplementation may influence these pathways, potentially affecting lipoma formation and growth." (PMID 40225498, 2025).
liver disease (3 papers, 2019 to 2020). "Lipoprotein lipase activity has been shown to inversely correlate with HCV RNA levels, and low apoC2 levels correlate with increased HCV infection and more advanced liver disease." (PMID 30884773, 2019). "Indeed, lipid disorders frequently accompany liver disease, with increased hepatic secretion of VLDL particles due to increased concentration of free fatty acids and glucose, and decreased VLDL clearance due to reduced activity of lipoprotein lipase." (PMID 32664348, 2020).
prediabetes (3 papers, 2019 to 2024). "Quantification of ΔTHR, LPL level and measurement of blood LPL activity will be informative to screen prediabetes and provide personalized care to high-risk individuals." (PMID 39557295, 2024). "H3K4me3 was enriched at the promoter of E2F1, LPL, SREBF2, SCD1, PPARG and IL6 in lean normoglycemic compared to morbid obese subjects with prediabetes." (PMID 30958852, 2019).
Renal insufficiency (3 papers, 2016 to 2021). A reduction in the level of performance of the kidneys in areas of function comprising the concentration of urine, removal of wastes, the maintenance of electrolyte balance, homeostasis of blood pressure, and calcium metabolism. "A decrease of apolipoprotein C-II/C-III ratio due to a disproportionate increase of apolipoprotein C-III in plasma is a possible cause of lipoprotein lipase inactivation in patients with renal insufficiency." (PMID 27127544, 2016).
rheumatoid arthritis (3 papers, 2022 to 2024). A chronic, systemic autoimmune disorder characterized by inflammation in the synovial membranes and articular surfaces. "Interestingly, while the inflammatory state may affect preheparin LPL mass in rheumatoid arthritis, MIF-regulated LPL transcription is independent of inflammation." (PMID 38973609, 2024).
spinal muscular atrophy (3 papers, 2020 to 2024). A motor neuron disease that affect the muscles, and characterized by muscle weakness and atrophy resulting from progressive degeneration and irreversible loss of the anterior horn cells in the spinal cord (i.e., lower motor neurons) and the brain stem nuclei. "Presently, three AAV-vector based gene therapeutics are available as Glybera, treating Lipoprotein Lipase (LPL)-deficiency, Luxturna, treating Retinal Pigment Epithelial (RPE) 65-related retinal dystrophy, and Zolgensma, treating Spinal Muscular Atrophy (SMA)." (PMID 33383947, 2020). "This includes hemophilia A and lipoprotein lipase deficiency, as well as several neurological conditions such as Duchenne muscular dystrophy (DMD), spinal muscular atrophy (SMA), aromatic L-amino acid decarboxylase (AADC) deficiency, and Leber congenital amaurosis (LCA)." (PMID 39286667, 2024).
triple-negative breast carcinoma (3 papers, 2014 to 2021). An invasive breast carcinoma which is negative for expression of estrogen receptor (ER), progesterone receptor (PR), and human epidermal growth factor receptor 2 (HER2). "It has been recently reported that certain cancer cells such as aggressive triple-negative breast cancer cell lines express markers of lipolysis (lipoprotein lipase, LPL) and exogenous fatty acid uptake (CD36), concomitantly with markers of de novo lipogenesis (FASN)." (PMID 25215509, 2014).
visceral leishmaniasis (3 papers, 2014 to 2018). A severe form of leishmaniasis characterized by irregular bouts of fever, substantial weight loss, swelling of the spleen and liver, and anemia (which may be serious). "Recently, Carvalho and colleagues found that some components of lipid metabolism had an association with lipoprotein lipase (LPL), apolipoprotein E (ApoE), and PPARα gene polymorphisms and presented the risk markers of visceral leishmaniasis (VL)." (PMID 29875768, 2018). "In addition, lipoprotein lipase gene polymorphism is associated with high levels of triglycerides and very low‐density lipoproteins (VLDL) and low levels of high‐density lipoprotein (HDL), which favor the development of visceral leishmaniasis." (PMID 28349644, 2017).
vitamin D deficiency (3 papers, 2013 to 2023). A nutritional condition produced by a deficiency of VITAMIN D in the diet, insufficient production of vitamin D in the skin, inadequate absorption of vitamin D from the diet, or abnormal conversion of vitamin D to its bioactive metabolites. "Subjects with vitamin D deficiency display a reduction of LPL activity and a compensatory secretion of betatrophin and then lead to the increasing of serum lipids levels and this effect disappeared when vitamin D is not deficient." (PMID 27716289, 2016). "Of interest, subjects in both vitamin D deficiency and insufficiency groups had significantly lower LPL values than those in vitamin D sufficiency group (P < 0.05)." (PMID 23320821, 2013).
abdominal aortic aneurysm (2 papers, 2021 to 2023). Enlargement and ballooning of the vessel that supplies arterial blood to the abdomen, pelvis and legs. "LPL variants were also associated with risks for low abdominal aortic aneurysms (OR = 0.64, 95% CI = 0.44–0.94, p = 0.022)." (PMID 34834523, 2021). "We found a weak association between TG-lowering therapies and aortic (ANGPTL3, 0.51, 0.29–0.89) and abdominal aortic aneurysms (LPL, 0.64, 0.44–0.94)." (PMID 34834523, 2021). "For example, several (5/39) of the significant genes (including LPL, IFI44L, ACKR2, HBA1, and HBA2) have also been found to be differently expressed in abdominal aortic aneurysms." (PMID 36836499, 2023).
acute kidney injury (2 papers, 2021 to 2024). Sudden and sustained deterioration of the kidney function characterized by decreased glomerular filtration rate, increased serum creatinine or oliguria. "Additionally, in a cisplatin-induced acute kidney injury mouse model, increased ANGPTL4 expression was observed alongside reduced LPL activity, predominantly in the proximal tubular segments, suggesting that ANGPTL4 may be involved in the AKI mechanism by regulating LPL activity." (PMID 39840089, 2024).
AL amyloidosis (2 papers, 2022 to 2023). AL Amyloidosis is a plasma cell disorder characterized by the aggregation and deposition of insoluble amyloid fibrils derived from misfolding of monoclonal immunoglobulin light chains usually produced by a plasma cell tumor. "The diseases classically associated with paraproteinemia include monoclonal gammopathy of undetermined significance, multiple myeloma, Waldenstrom Macroglobulinemia/lymphomplasmacytic lymphoma (MW/LPL), cryoglobulinemia, and light chain amyloidosis." (PMID 37760410, 2023). "An estimated 7.5% of patients with LPL/WM are also diagnosed with AL amyloidosis at some point in the course of their disease, and a very small fraction of patients with IgM monoclonal gammopathy of undetermined significance (MGUS) will develop AL amyloidosis." (PMID 36591532, 2022). "The workup for AL amyloidosis, as well as LPL/WM, includes a bone marrow biopsy." (PMID 36591532, 2022).
Anxiety (2 papers, 2022 to 2025). Intense feelings of nervousness, tension, or panic often arise in response to interpersonal stresses. "The results had a normal distribution, confirming the suitability of subsequent analysis, and showed a positive association between LPL rs326 gene polymorphism, anxiety, and participants with MetS, but not other psychometric dimensions." (PMID 41464486, 2025). "However, a significant difference in LPL-Anxiety between genotypes GA-GG (p < 0.05) was found." (PMID 41464486, 2025).
asthma (2 papers, 2021 to 2024). "In this study, we found that TG levels driven by the APOC3, and LPL targets were associated with an increased risk of asthma." (PMID 38961500, 2024). "Consistent with previous studies, we found that an increased TG level driven by the APOC3(OR = 1.0086, 95%CI: 1.0037–1.0135) and LPL (OR = 1.0040, 95%CI: 1.0001–1.0078) target were associated with an increased risk of asthma." (PMID 38961500, 2024). "The elevated triglyceride (TG) levels associated with the APOC3, and LPL targets were found to increase asthma risk." (PMID 38961500, 2024). "Similarly, an increased TG level driven by LPL was associated with an increased risk of asthma (LPL: OR = 1.0040, 95%CI: 1.0001–1.0078)." (PMID 38961500, 2024).
autism (2 papers, 2021 to 2023). Persistent deficits in social interaction and communication and interaction as well as a markedly restricted repertoire of activity and interest as well as repetitive patterns of behavior. "Interestingly, WES analysis identified in the male partner a pathogenic variant in the LPL gene that is emerging as a novel candidate gene for autism." (PMID 37628702, 2023). "LPL was identified as a gene affected in multiple hyperlipidemic conditions including familial combined hyperlipidemia and is an autism candidate gene." (PMID 34504056, 2021).
carotid atherosclerosis (2 papers, 2022 to 2023). A thickening and loss of elasticity of the walls of carotid arteries that occur with formation of atherosclerotic plaques. "We additionally set out to study how circulating LPL relates to the lipid profile, subclinical carotid atherosclerosis, and several cardiovascular risk factors." (PMID 36982268, 2023).
cognitive decline (2 papers, 2021 to 2022). "Beside pPE and LPL changes, alterations in plasma PC and SM levels accompanying cognitive decline were also reported in previous studies." (PMID 34201969, 2021). "Similarly, higher levels of AXL, MERTK, GAS6, LPL, CST7 and CSF1 predicted slower tau accumulation and/or cognitive decline in the A+T+ group." (PMID 37118533, 2022).